RAF1 (Raf-1 proto-oncogene, serine/threonine kinase)
Diseases named in the same sentence as RAF1 in open-access papers (continued):
Sharing a sentence is not in itself a finding about the gene and the disease.
thyroid cancer (12 papers, 2014 to 2024). "For example, highly expressed miR-195 inhibited the expression of RAF1 and blocked the proliferation of thyroid cancer." (PMID 39076089, 2024). "Of note, activating RAF1 fusions are also found in a small proportion of thyroid carcinomas, prostatic adenocarcinomas, and pilocytic astrocytomas." (PMID 32123303, 2020). "This miRNA is downregulated in thyroid cancer and directly targets RAF1 to block thyroid cancer cell proliferation." (PMID 31312183, 2019). "In thyroid cancer, Raf1, a direct target of miR-195, was significantly upregulated in thyroid carcinomas compared to benign tumors and miR-195 overexpression dramatically decreased the protein level of Raf1 and inhibited cell proliferation in thyroid cancer." (PMID 31870440, 2019). "Recently, RAF1 overactivation has been shown to occur in various cancers (e.g., breast, lung and thyroid cancers) and is regarded as a critical marker in cancer treatment." (PMID 30201903, 2018). "Notably, thyroid cancers have the highest frequency of recurrent kinase fusions (63/498, 13%), and all fusion events including ALK, BRAF, MET, NTRK1, NTRK2, RAF1 and RET are mutually exclusive in this cancer type." (PMID 25204415, 2014).
breast tumor (11 papers, 2013 to 2021). "ERα+ breast tumor xenografts with a constitutive active Raf-1/MAPK signaling developed spontaneous lung metastases through the clonal expansion of cancer cells expressing a NOTCH3 reprogramming network." (PMID 30180881, 2018). "These alterations lead to accumulation of genomic aberrations such as RAF1 gene amplification and activation of RAF1-ERK-β-catenin signaling promoting the aggressiveness of breast tumors." (PMID 27793053, 2016). "EZH2 promoted expansion of breast tumor initiating cells through RAF1-p-ERK-β-catenin pathway activation." (PMID 24345883, 2013). "Inhibitors of RAF1-ERK signaling, such as sorafenib and AZD6244, are plausible therapeutic agents to eradicate breast tumor initiating cells." (PMID 25520914, 2014). "For example, study shows EZH2 up-regulating RAF1-ERK-β-catenin pathway, leading to promoting survival and proliferation of breast tumor initiating cells." (PMID 25520914, 2014). "Moreover, compared with normal tissues, Raf-1, ERK and p-ERK were overexpressed in malignant breast tumor tissues." (PMID 29403024, 2018).
non-small cell lung carcinoma (11 papers, 2009 to 2024). A group of at least three distinct histological types of lung cancer, including non-small cell squamous cell carcinoma, adenocarcinoma, and large cell carcinoma. "For example, ERK phosphorylation as a marker of Ras activity has shown prognostic value in non-small cell lung cancer, and exposure to mold proteases stimulated mucin production in airway epithelial cells through Ras/Raf1/ERK signal pathway." (PMID 34869091, 2021). "Dasgupta and coworkers demonstrated that human non-small cell lung cancer (NSCLC) tumor tissues had high levels of Rb-Raf-1 complexes in tumors relative to adjacent normal lung tissue, suggesting that perhaps the Rb-Raf-1 pathway contributes to the genesis of these tumors." (PMID 19712465, 2009). "miR-7-5p is more of a tumor suppressor that represses oncogenic proteins such as EGFR, IGF1R, IRS-1, IRS-2, RAF1, PIK3CD, mTOR, and PI3K, in various cancers including PDAC, liver, breast, non-small cell lung carcinoma (NSCLC), colorectal (CRC) and ovarian." (PMID 31510100, 2019).
cardiomyopathy (10 papers, 2017 to 2025). A disease of the heart muscle or myocardium proper. "The relatively high frequency of HCM in patients with RAF1 mutations further emphasizes the importance of early genetic screening and targeted surveillance for cardiomyopathy in this group." (PMID 39596663, 2024). "Surprisingly, neoplasms were also linked to cardiomyopathies (12.2%) dominated by the RAF1 gene (41%)." (PMID 36385157, 2022). "When compared with the pathogenicity of the SNPs through annotation with the clinVar database, only one heterozygous SNP in RAF1 from child 2 was suggested to be pathogenic and related to cardiomyopathy dilated." (PMID 34184986, 2021). "We find that the combinatorial interactions of CMs, ECs and cardiac fibroblasts underlie the pathogenesis of RAF1-mutant NS-associated cardiomyopathy." (PMID 28548091, 2017). "We identified two variants in conserved miRNA binding sites of genes previously implicated in cardiomyopathy: SCN5A (chr3:38589677) and RAF1 (chr3:12625903)." (PMID 40791945, 2025). "The most significant form of cardiomyopathy in NS is HCM, and it is driven mostly by RAF1 and RIT1 mutations that promote abnormal cardiac muscle growth through Ras/MAPK hyperactivation." (PMID 39596663, 2024). "Cardiomyocyte-specific expression of dominant-negative RAF1 in mice increases cardiomyocyte apoptosis, with cardiomyopathy developing in response to pressure-overload, consistent with a cardioprotective role of RAF1." (PMID 35147166, 2022). "Our cases do not present any sign of cardiomyopathy; hence, we rule out RAF1 as a likely cause of PME." (PMID 39156922, 2024). "The majority of the VUS has been identified in genes previously having been reported to be associated with cardiac channelopathies (SCN5A, AKAP9, RYR2) and cardiomyopathies (RBM20, RAF1, DSG2)." (PMID 33789662, 2021). "Moreover, aberrant RAF1 activity in CMs or cardiac fibroblasts, but not ECs, contributes to pressure overload-induced fibrosis in NS-cardiomyopathy." (PMID 28548091, 2017).
heart failure (10 papers, 2011 to 2024). Inability of the heart to pump blood at an adequate rate to meet tissue metabolic requirements. "Heart failure-promoting activities of RKIP involve the dual functions of RKIP as a RAF1 inhibitor and GRK2 inhibitor." (PMID 35203304, 2022). "In vivo studies in mice indicate that RAF1 is cytoprotective in cardiomyocytes, since overexpression of a dominant-negative form of RAF1 in cardiomyocytes or cardiomyocyte-specific RAF1 knockout leads to increased cardiomyocyte apoptosis and heart failure." (PMID 36331065, 2022). "A RAF1-deficient male and a RASA1-deficient male survived from severe heart failure by surgical interventions in early life." (PMID 36002837, 2022). "Therefore, the net effect of the dual RAF1 and GRK2 inhibition by RKIP in vivo is a detrimental cardiac phenotype, which predisposes to cardiac fibrosis, cardiac dilation and heart failure." (PMID 35203304, 2022). "Up-regulation of BRAF in separate cohorts of heart failure patients, with selective up-regulation of BRAF and down-regulation of RAF1 and ARAF isoforms in patients with dilated cardiomyopathy, suggests that the changes are a key feature of a failing heart." (PMID 35147166, 2022). "Inhibition of the pro-survival RAF1-MAPK pathway and cardiotoxic lipid overload both contribute to RKIP-enhanced cardiomyocyte apoptosis and the heart failure phenotype." (PMID 35203304, 2022). "RAF1 and ARAF mRNAs are both down-regulated in dilated cardiomyopathy, although there may be differential regulation of RAF1 in some forms of heart failure." (PMID 36331065, 2022). "RKIP induces heart failure by its dual functions as a GRK2 inhibitor and RAF1 inhibitor." (PMID 35203304, 2022). "Notably, the severity of RKIP-induced symptoms of heart failure could be a consequence of the dual activity of RKIP as GRK2 and Raf1-Erk1/2 axis inhibitor." (PMID 30687708, 2018). "BRAF and RAF1 (but not ARAF) mRNA and protein were significantly up-regulated in samples from a cohort of 12 patients with heart failure of mixed non-ischaemic aetiology compared with normal controls." (PMID 35147166, 2022).
leukemia (9 papers, 2014 to 2025). A malignant (clonal) hematologic disorder, involving hematopoietic stem cells and characterized by the presence of primitive or atypical myeloid or lymphoid cells in the bone marrow and the blood. "BCR-ABL1 and hyperactive FLT3 are tyrosine kinases that causally contribute to the development of leukemia and induce RAF1 and BCL-XL." (PMID 34298678, 2021). "RAF1 is important in inducing apoptosis in leukaemia cells and is related to relapse-free survival of AML patients." (PMID 34131166, 2021). "We investigated the expression levels of MKRN2 and RAF1 in normal and malignant hematopoietic cells, and leukemia cell lines." (PMID 24675897, 2014). "We also demonstrated expressions of MKRN2 and RAF1 in leukemia cell lines of B-ALL, T-ALL, AML, CML, NK and MK lineages (n = 2–3)." (PMID 24675897, 2014). "Our results demonstrated ubiquitous mRNA expression of MKRN2 and RAF1 in normal hematopoietic cells, embryonic stem cell lines, primary leukemia and leukemic cell lines." (PMID 24675897, 2014). "The results indicated that 2b inhibited at values ranging from 70% to 98% the biochemical activity of IKK-α (70%), IRK (86%), PKC-β (79%), RAF-1 (79%), Src (94%), TRKA (98%) kinases, all of them found involved in leukemia initiation and development." (PMID 32075099, 2020). "The expression levels of MKRN2 were generally higher in leukemia samples (P<0.05 in Ph–B-ALL, Ph+B-ALL, T-ALL and AML samples) compared with those in age-matched normal BM cells (n = 9), whilst RAF1 was higher in Ph–B-ALL and AML samples (P<0.05)." (PMID 24675897, 2014). "In primary leukemia samples obtained from BM of patients, we showed positive expressions of MKRN2 and RAF1 in B-ALL Philadelphia chromosome (BCR/ABL or Ph) positive and negative, T-ALL, AML and CML samples (n = 5–22)." (PMID 24675897, 2014). "It is anticipated that a larger sample size of each leukemia subtype would be required to accurately address the relationship between MKRN2 and RAF1, as well as between specific translocations such as BCR-ABL." (PMID 24675897, 2014).
sarcoma (9 papers, 2016 to 2025). A usually aggressive malignant neoplasm of the soft tissue or bone. "Trametinib should, in theory, be effective in treating sarcomas with RAF1 mutations, nevertheless, there is exceedingly rare data regarding the same." (PMID 40556788, 2025). "This case exemplifies the value of molecular characterisation of soft tissue sarcoma and adds to the already sparse literature for RAF1 mutated sarcomas." (PMID 40556788, 2025). "We present a case report of a patient with metastatic RAF1 gene mutation sarcoma who was successfully treated with a combination of trametinib and doxorubicin." (PMID 40556788, 2025). "Repeat biopsy and next-generation sequencing (NGS) were suggestive of PDZRN3/RAF1 fusion mutated sarcoma." (PMID 40556788, 2025). "Sarcomas with RAF1 mutations are extremely rare and so far, the treatment strategies are not known." (PMID 40556788, 2025). "RAF1 amplifications were also observed in two patients each with CRC (n = 2, 8.0%) and sarcoma (n = 2, 8.0%)." (PMID 38137485, 2023).
cutaneous melanoma (8 papers, 2010 to 2024). A primary melanoma arising from atypical melanocytes in the skin. "Specifically, RAF1 mutations were frequently observed in skin cutaneous melanoma (5.41%, 24/444) and uterine corpus endometrial carcinoma (4.54%, 24/529), whereas RAF1 amplification was highly concentrated in bladder tumors (10.71%, 44/411)." (PMID 38111008, 2023). "In comparison to RAF-1, activating mutations of B-RAF are relatively common in a variety of malignancies, particularly in cutaneous melanoma." (PMID 33898322, 2021). "Two of the rearrangements affecting RAF1 were structurally similar to RAF1 fusions known from cutaneous melanoma." (PMID 33441414, 2021). "In our cases of primary cutaneous melanoma with activating RAF1 fusions, a distinctive growth pattern, such as the fascicular pattern of ALK1-fused Spitz tumors, was not seen." (PMID 32123303, 2020).
neuroblastoma (8 papers, 2015 to 2024). Neuroblastoma (NB) is the most common solid, extracranial childhood tumor. "Collectively, these findings demonstrated that c-Jun/Fra-1 dimer is critical for neuroblastoma cell growth and that HDACIs act as effective suppressors of the two oncogenes through transcriptionally downregulating MKK7 and Raf1." (PMID 26734995, 2016). "Mapping the upstream regulator networks that drive DE genes in highly MNA cells compared with MYCN single copy cells elucidated several central nodes not previously linked to MNA neuroblastoma (e.g. HRAS, MAPK1, RAF1, NEUROG1 and ER)." (PMID 26673823, 2015).
renal cell carcinoma (7 papers, 2004 to 2023). "Renal Cell Carcinoma Pathway assigned of 49/66 CNA genes RAF1 (16/26) and VHL (14/26) as G1 top-ranks with Fisher’s exact test p-values of 0.00228 and 0.0004437 (respectively) and SOS2 (7/20), HGF (4/20) and BRAF (3/20) as G3 top-ranks with p-values of 0.17, 0.51 and 0.075, respectively." (PMID 28486536, 2017). "Sorafenib (SFN) (BAY 43-9006; Nexavar), which potently inhibits both the c-Raf (Raf-1) and b-Raf isoforms, was approved by the FDA in 2005 for treatment of advanced renal cell carcinoma." (PMID 29113345, 2017). "In renal cell carcinoma, MAPK activation correlated with MAPK kinase activation and Raf-1 activation, while for hepatocarcinomas a relationship was reported between ERK1/2 activation and expression of the transcription factor c-Fos and cyclin D1." (PMID 15280923, 2004). "Moreover, SOR, as a Raf-1 inhibitor, can disturb the RAS/RAF/MEK/ERK signaling pathway in renal cell carcinoma." (PMID 34513674, 2021).
Alzheimer disease (6 papers, 2011 to 2024). A progressive, neurodegenerative disease characterized by loss of function and death of nerve cells in several areas of the brain leading to loss of cognitive function such as memory and language. "We examined the phosphorylation status of RAF1 at S338 in these cellular HD models to determine if signaling is dysregulated, as has been observed previously in Alzheimers disease (AD) patient brains and a mouse model of AD." (PMID 23209424, 2012). "Elevated RAF1 S338 phosphorylation has been reported previously in Alzheimer's disease (AD) patient brains and a mouse model of AD." (PMID 23209424, 2012). "Furthermore, we report that galantamine used in Alzheimer’s disease treatment and the antiemetic drug granisetron can bind to RAF1–BRAF interface." (PMID 38216592, 2024). "Additionally, a drug used in Alzheimer's disease can bind to RAF1 and BRAF interface." (PMID 38216592, 2024). "Seven of these genes are Alzheimer’s disease-related, six are down-regulated with both Apoer2-ICDs (COX7A2L, FZD2, KIF5A, MAP2K2, PSENEN, RAF1) and one with only the Apoer2-ICD[Δ19] (SLC39A9)." (PMID 37461529, 2023).
dilated cardiomyopathy (6 papers, 2016 to 2024). Cardiomyopathy which is characterized by dilation and contractile dysfunction of the left and right ventricles. "The mutation identified in RAF1 is a known natural variant but has been reported to be associated with dilated cardiomyopathy." (PMID 39156922, 2024). "ARAF, BRAF and RAF1 transcripts were readily detected in human hearts, but only BRAF transcript expression was significantly increased in dilated cardiomyopathy samples; ARAF and RAF1 transcripts showed decreased expression." (PMID 35147166, 2022). "Taken together, Tg-RKIP mice with myocardium-specific expression of the dual RAF1 and GRK2 inhibitor, RKIP, developed a phenotype of dilated cardiomyopathy with features of cardiomyocyte hypertrophy and cardiomyocyte apoptosis." (PMID 35203304, 2022).
lymphoma (6 papers, 2014 to 2021). A malignant (clonal) proliferation of B- lymphocytes or T- lymphocytes which involves the lymph nodes, bone marrow and/or extranodal sites. "We thus concluded that the combined inhibition of ALK and RAF1 triggered enhanced autophagy, through relieving inhibition of the ULK1 protein, and may represent a more effective therapy, in comparison with single crizotinib treatment, for ALK+ ALCL lymphomas." (PMID 34685497, 2021).
papillary thyroid cancer (6 papers, 2014 to 2022). "ERBB3/ERBB4/RAF1 kinases were activated in papillary carcinoma compared to other variants, PAK3/PAK6/CDK1 kinases were activated in NOS, and PRKACA/PRKACB/PRKACG kinases were activated in differentiation variants." (PMID 35659036, 2022). "In a word, LINC00460 promoted the papillary thyroid cancer progression by regulating the LINC00460/miR-485-5p/Raf1 axis, which provides a theoretical basis on PTC markers and potential therapeutic targets." (PMID 31870440, 2019). "Overall, LINC00460 promoted the papillary thyroid cancer progression by regulating LINC00460/miR-485-5p/Raf1 axis, which might provide novel biomarkers for PTC treatment." (PMID 31870440, 2019).
pilocytic astrocytoma (6 papers, 2013 to 2020). Pilocytic astrocytoma is a rare subtype of low-grade glioma of the central nervous system characterized by a well circumscribed, often cystic, brain tumor with a discrete mural nodule and long, hair-like projections that extend from the neoplastic astrocytes. "Fusions involving CRAF (RAF1), a human homolog of the v-raf gene implicated in cell proliferation and survival, are infrequently identified in pLGG, most commonly in pilocytic astrocytoma." (PMID 32164789, 2020). "The presence of BRAF and RAF1 fusions has been reported to activate mitogen activated kinase-like protein (MAPK) in pilocytic astrocytoma." (PMID 25473895, 2015). "On a cautionary note, most pilocytic astrocytomas (a distinct diagnosis, but related to anaplastic astrocytoma) carry RAF1 or BRAF rearrangements; thus it is possible that the D538-MG cell line (harboring BCL6/RAF1) was actually derived from a misdiagnosed pilocytic astrocytoma." (PMID 23637631, 2013).
skin cancer (6 papers, 2009 to 2024). "In agreement with our results, Jong-Eun Kim has also implicated the RAF1 pathway in the MAPK signaling in skin cancer cells and found that cyanidin suppresses ultraviolet B-induced skin cancer by targeting RAF1." (PMID 26649302, 2015). "More work is needed to determine the effect of CDC25A on Raf-1 phosphorylation and how Raf-1 may impact Akt activation in skin cancer." (PMID 32934772, 2020).
triple-negative breast carcinoma (6 papers, 2015 to 2021). An invasive breast carcinoma which is negative for expression of estrogen receptor (ER), progesterone receptor (PR), and human epidermal growth factor receptor 2 (HER2). "Furthermore, another more recent study by our group indicated that long-term treatment of lapatinib in triple-negative breast cancer cells increases IL6 expression through miRNA-7-dependent activation of Raf-1 signaling." (PMID 27694691, 2016). "Taken together, these integrated proteomic in vitro and in vivo studies indicate that the synthetic Raf1/ERK dual inhibitor CY-9d and its combined administration with an HSP90 inhibitor may be potential therapeutic strategies for the treatment of triple negative breast cancer." (PMID 29262632, 2017).
adenoma (5 papers, 2004 to 2025). A neoplasm arising from the epithelium. "Finally, between LSTs and adenomas, the Ras and Raf1 signaling pathway exhibit opposite epimutation patterns with a hypomethylation profile in flat lesions versus a hypermethylation status for adenomas." (PMID 40943367, 2025). "Using the Sengenics CTA protein array, pooled benign controls (n = 2, adenomas) showed detectable autoantibodies (Z-score > 3) against five antigens (AURKA, CTAG1A, CYP450 3A4, MAGEA4 and RAF1)." (PMID 34681879, 2021).
cardio-facio-cutaneous syndrome (5 papers, 2012 to 2023).